DLAT (dihydrolipoamide S-acetyltransferase)
Description:
The pyruvate dehydrogenase (PDH) complex, catalyzes the overall conversion of pyruvate to acetyl-CoA and CO(2), and thereby links cytoplasmic glycolysis and the mitochondrial tricarboxylic acid (TCA) cycle (Probable). It contains multiple copies of three enzymatic components: pyruvate dehydrogenase (E1), dihydrolipoamide acetyltransferase (E2) and dihydrolipoamide dehydrogenase (E3); (Probable). Within this complex, the catalytic function of this enzyme is to accept, and to transfer to coenzyme A, acetyl groups from acetyl-lipoyl moiety generated by the pyruvate dehydrogenase, leading to acetyl-CoA formation (Probable).
Synonyms: PBC; PDC-E2; PDCE2; DLTA; E2
Tractability: Small molecule: a structure with a bound ligand is known; it has a high-quality binding pocket. PROTAC: ubiquitination databases record sites on it; its protein half-life has been measured; a small molecule that binds it is known.
Target class: Enzyme; Transferase
Gene: Protein-coding gene on chromosome 11 (112,025,033 to 112,064,404, forward strand). Ensembl gene ENSG00000150768.
Subcellular location: Mitochondrion matrix
Subcellular location (Human Protein Atlas): Mitochondria; Connecting piece
Pathways (Reactome):
Metabolism: PDH complex synthesizes acetyl-CoA from PYR; Regulation of pyruvate dehydrogenase (PDH) complex
Metabolism of proteins: Protein lipoylation
Signal Transduction: Signaling by Retinoic Acid
Gene Ontology:
Molecular function: dihydrolipoyllysine-residue acetyltransferase activity; identical protein binding; protein binding; acetyltransferase activity; acyltransferase activity
Biological process: pyruvate decarboxylation to acetyl-CoA; tricarboxylic acid cycle; pyruvate catabolic process
Cellular component: mitochondrion; pyruvate dehydrogenase complex; mitochondrial matrix
Genetic constraint (gnomAD): Loss-of-function variants: 34 observed, 59.61 expected, observed/expected ratio (o/e) 0.57, 90% interval 0.43 to 0.76. The upper end of that interval is the gene's LOEUF score, 0.76, which puts it in group 3 of 6, group 1 being the genes least tolerant of losing a copy. Missense variants: 693 observed, 795.94 expected, observed/expected ratio (o/e) 0.87, 90% interval 0.82 to 0.93. Synonymous variants: 252 observed, 285.28 expected, observed/expected ratio (o/e) 0.88, 90% interval 0.8 to 0.98.
Gene-disease validity (ClinGen):
ClinGen rates the evidence that DLAT causes each of these diseases.
Leigh syndrome (autosomal recessive): Moderate. A progressive neurological disease defined by specific neuropathological features associating brainstem and basal ganglia lesions.
Homologues: Orthologues: chimpanzee DLAT (99% identical), macaque DLAT (98% identical), guinea pig DLAT (91% identical), dog DLAT (89% identical), pig DLAT (89% identical), rabbit DLAT (89% identical), mouse Dlat (85% identical), rat Dlat (83% identical), zebrafish dlat (72% identical), tropical clawed frog dlat (71% identical), Caenorhabditis elegans dlat-1 (42% identical), Drosophila melanogaster muc (39% identical). Paralogues in human: PDHX (31% identical), DLST (21% identical), DBT (19% identical).
Diseases named in the same sentence as DLAT in open-access papers:
DLAT is named in the same sentence as 135 diseases in open-access papers, as found by Europe PMC text mining. Sharing a sentence is not in itself a finding about the gene and the disease. The quoted sentences say what the papers report.
gastric cancer (22 papers, 2020 to 2025). A primary or metastatic malignant neoplasm involving the stomach. "A number of malignancies, including lung cancer, gastric cancer and colon cancer, have been associated with high expression of DLAT in various tumors." (PMID 36620594, 2022). "DLAT, a mitochondrial protein involved in glucose metabolism, is overexpressed in gastric cancer cells and has been linked to the development, proliferation, and energy metabolism of gastric cancer cells." (PMID 36092880, 2022). "For example, silencing DLAT inhibits gastric cancer cell proliferation and migration, while DLAT overexpression promotes liver hepatocellular carcinoma cell growth by targeting autophagy." (PMID 40136693, 2025). "Our results also showed that DLAT was mainly enriched in oxidative phosphorylation, citric acid cycle, pyruvate metabolism and other substances and energy metabolic processes in gastric cancer." (PMID 38898987, 2024). "DLAT imbalance influences cell proliferation and migration, and silencing DLAT has been shown to increase pyruvate levels and reduce cancer growth in gastric cancer." (PMID 38722401, 2024). "DLAT was a subunit of pyruvate dehydrogenase complex, and siRNA studies supported the role of DLAT in gastric cancer proliferation and carbohydrate metabolism." (PMID 36891324, 2023). "It is found that DLAT is upregulated in gastric cancer cells, and the breaking down of DLAT brings about an increase in cellular pyruvate and a decrease in cell proliferation by almost 20–45%." (PMID 36949759, 2023). "DLAT is found to regulate cell proliferation and carbohydrate metabolism in gastric cancer cells and B-cell chronic lymphocytic leukemia cells." (PMID 36386799, 2022). "DLAT is one of three mitochondrial proteins found to be upregulated in eight of 11 gastric cancer cell lines." (PMID 36338763, 2022). "The results tentatively proved the functionality of DLAT in regulating P-CA gene expression in gastric cancer." (PMID 36229828, 2022). "Some of these markers have been identified for their potential functions in cancer: FDX1 can be activated by SF1 and cJUN in Leydig cells, CDKN2a usually functions as a tumor suppressor in many cancers, and DLAT has also been reported to be an oncogene in gastric cancer." (PMID 37190215, 2023). "In addition, DLAT was increased in gastric cancer, and siRNA-mediated knockdown of DLAT could increase the pyruvate levels." (PMID 37330494, 2023). "Among them, DLD and PDHA1 were differentially expressed in colon cancer, and DLAT, DLD, and PDHA1 were differentially expressed in gastric cancer and liver cancer." (PMID 36960059, 2023). "We conducted molecular experiments to validate our findings, and the results of Western blot analysis revealed notable disparities in the expression levels of FDX1, LIAS, DLAT, DLST, GCSH, PDHB and PDHA1 in gastric cancer cells between the CSRS‐Low (AGS) and CSRS‐High (HGC‐27) subtypes." (PMID 38898987, 2024). "Furthermore, ovarian cancer patients with relatively high DLAT expressions presented relatively poor OS, PPS, and PFS, while patients of gastric cancer with relatively high DLAT expressions showed relatively poor OS and PPS." (PMID 36949759, 2023).
breast carcinoma (15 papers, 2022 to 2026). "ATP7B and DLAT are both mutated in breast cancer samples, with the most common mutation being missense mutation." (PMID 37180167, 2023). "The univariate Cox regression demonstrated that LIPT1, PDHA1, and DLAT as predictor to poor survival and further classified breast cancer samples into three geneClusters (geneClusterA, geneClusterB and geneClusterC)." (PMID 37353799, 2023). "HPAanalyze, a visualization R package, presented the expression of ATP7B and DLAT proteins in myoepithelial and glandular cells in breast cancer tissue using a heatmap." (PMID 37180167, 2023). "Two essential copper-related genes, ATP7B and DLAT, were selected to construct the scoring model to predict breast cancer patient survival." (PMID 37180167, 2023). "Immunohistochemistry staining showed high protein expression of ATP7B and DLAT in breast cancer samples." (PMID 37180167, 2023). "Specifically, we analyzed the protein expression, the related genes and the metabolic pathways of the essential copper-related genes, namely ATP7B and DLAT, in breast cancer samples." (PMID 37180167, 2023). "KIAA1735 gene and DLAT gene are linked in a tail to head manner, and KIAA1735 gene is deleted in breast cancer." (PMID 36699089, 2022). "qPCR results showed that two model lncRNAs (USP2-AS1, NIFK-AS1) and three Cuproptosis genes (FDX1, PDHA1, DLAT) expressed differently between 10 pairs of breast cancer tissue samples and adjacent samples." (PMID 36699089, 2022). "Besides, we wonder what critical role ATP7B and DLAT played in breast cancer, given that these genes are essential for copper homeostasis and cuproptosis." (PMID 37180167, 2023). "FDX1, PDHA1 and DLAT also significantly down regulated in breast cancer." (PMID 36699089, 2022). "Furthermore, recent studies have shown that DLAT expression is high in patients who exhibit resistance to anti-PD-L1/PD-1 treatments, implying that DLAT could serve as a predictive marker for breast cancer (BRCA) resistance to immunotherapy." (PMID 39702350, 2024). "To reveal additional links to the biological function of ATP7B and DLAT in breast cancer development, we utilized the functional module of LinkedOmics to analyze genes that were positively or negatively correlated with ATP7B and DLAT." (PMID 37180167, 2023). "We found that genes DLAT, SLC31A1, ATP7A and ATP7B were significantly related to the overall survival (OS) of breast cancer patients in univariate Cox regression analysis." (PMID 35996075, 2022). "Since DLAT, SLC31A1, ATP7A and ATP7B were all found to be related to prognosis in breast cancer, a combined prognostic model aggregating more cuproptosis-related genes and clinical features is expected in future." (PMID 35996075, 2022). "FDX1 (P < 1E‐12), LIAS (P = 2.22E‐16), LIPT1 (P < 1E‐12), DLD (P < 5.46E‐09), DLAT (P = 3.14E‐02), PDHA1 (P = 1.15E‐07), MTF1 (P = 1.07E‐09), and GLS (P = 2.48E‐05) were downregulated in breast cancer, while PDHB (P = 5.04E‐07) and CDKN2A (P = 1.62E‐12) were upregulated." (PMID 39432636, 2024). "Intriguingly, the expression of ATP7B and DLAT were decreased and increased respectively in the basal-like subtype compared with non-cancerous samples, which is opposite to those in other breast cancer subtypes." (PMID 37180167, 2023). "We analyzed the expression pattern of CRGs in breast cancer tissues and non-tumor tissues based on TCGA and GTEx dataset, illustrating that CDKN2A, DLD, DLAT, MTF1 and PDHB expression were significantly elevated in breast cancer compared with their normal tissues." (PMID 36518756, 2022). "Additionally, it was discovered via research of the impact of gene expression patterns on overall survival in breast cancer that those expressing high levels of ATP7A, DBT, DLAT, DLD, GLS, PDHA1, and SLC31A1 had a bad prognosis." (PMID 36059516, 2022). "The expression of DLAT was not negatively correlated with DNA methylation levels in breast cancer." (PMID 40302799, 2025).
breast carcinoma (continued). "As cuproptosis-promoting genes, FDX1, LIAS, LIPT1, DLD, DLAT, and PDHA1 were under-expressed in breast cancer; at the same time, CDKN2A, which inhibited cuproptosis, was over-expressed in breast cancer, suggesting that cuproptosis might involve in the protective mechanism of BRCA." (PMID 39432636, 2024).
primary biliary cholangitis (13 papers, 2008 to 2025). Primary biliary cholangitis (PBC) is a chronic and slowly progressive cholestatic liver disease of autoimmune etiology characterized by injury of the intrahepatic bile ducts that may eventually lead to liver failure. "Interestingly, dihydrolipoamide S-acetyltransferase and pyruvate dehydrogenase complex of various microbes are associated in the pathogenesis of primary biliary cirrhosis, chronic active hepatitis, sarcoidosis, systemic sclerosis, ulcerative colitis, and autoimmune hepatitis." (PMID 29062305, 2017). "DLAT encodes an essential subunit E2 of pyruvate dehydrogenase complex (PDHC), which is the critical autoantigen in primary biliary cholangitis (PBC)." (PMID 37124062, 2023).
glioma (9 papers, 2022 to 2025). A benign or malignant brain and spinal cord tumor that arises from glial cells (astrocytes, oligodendrocytes, ependymal cells). "We exhibited that DLAT expression was increased in most tumors, especially in glioma, and affected the survival of tumor patients." (PMID 39574473, 2024). "As for the DLAT expression in different tumor grades, significant differences were observed in five cancer types, including glioma (GBMLGG), KIPAN, KIRC, brain lower grade glioma (LGG), and pancreatic adenocarcinoma (PAAD)." (PMID 37199628, 2023). "In glioma patients, the levels of CDKN2A, FDX1, DLD, DLAT, LIAS, LIPT1, and PDHA1 were significantly associated with the OS, disease-specific survival, and progression-free interval." (PMID 36579333, 2022). "Furthermore, cuproptosis-related genes (LIPT1, FDX1, and DLAT) have emerged as therapeutic targets in epilepsy and gliomas, underscoring its broad relevance." (PMID 41214704, 2025). "DLAT was mainly expressed in malignant cells at single cells in glioma tissues by TISCH." (PMID 39574473, 2024). "To validate the function of DLAT in glioma, we developed silenced DLAT A172 glioma cell lines." (PMID 39574473, 2024). "Additionally, we also analyzed the potential function and mechanism of DLAT in a variety of human cancers, and validated its oncogenic role in glioma cells." (PMID 39574473, 2024). "Furthermore, we performed an experimental study to verify the function of DLAT in glioma cells." (PMID 39574473, 2024). "Moreover, we validated the function of DLAT in glioma cells." (PMID 39574473, 2024). "Furthermore, Cox regression analysis in the TCGA database showed that FDX1, LIPT1, DLD, DLAT, SLC31A1, ATP7A, and DLST might be risk factors; however, LIAS, ATP7B, and GCSH were significant preventive factors for gliomas." (PMID 37515314, 2023). "Further analysis of the relationship between CRGs and the prognosis of gliomas revealed that high expression of FDX1, DLD, DLAT, and LIPT1 was associated with poorer survival in glioma patients, and high expression of CDKN2A and PDHA1 was significantly associated with better survival in gliomas." (PMID 36915038, 2023). "In GBMLGG, DLAT expression positively correlated with tumor grade; notably, IDH wild-type gliomas exhibited higher DLAT levels than their IDH mutant counterparts." (PMID 40302799, 2025). "The DLAT gene was highly expressed in 22 types of cancers, including glioblastoma multiforme (GBM), lower grade glioma (LGG), and kidney chromophobe (KICH)." (PMID 39574473, 2024).
liver cancer (8 papers, 2023 to 2025). An epithelial or non-epithelial malignant neoplasm that arises from the liver. "Additionally, we found that the expression of DLAT is significantly associated with the clinical pathological features of liver cancer patients, including pathologic T stage and pathological stage." (PMID 40302799, 2025). "For the first time, we found a significant positive correlation between DLAT expression and m6A regulatory factors in liver cancer, and that DLAT is associated with the PLK1 pathway, PI3K-AKT signaling pathway, Notch signaling pathway, WNT signaling pathway, and Aurora B pathway." (PMID 40302799, 2025). "We further validated the expressions of the CRGs in liver cancer cell lines and related normal cells and found that the expression of DLAT and DLA are much higher and FDX1 lower in cancer cell lines compared to normal cells." (PMID 37608927, 2023). "The cuproptosis-related gene Dihydrolipoamide S-Acetyltransferase (DLAT) were significantly upregulated in liver cancer tissues." (PMID 37828099, 2023). "Therefore, the crosstalk between m6A RNA modification and DLAT expression in liver cancer needs to be further characterized in future studies, which will be critical to evaluate the potential of using m6A and its regulators for early cancer diagnosis." (PMID 40302799, 2025). "Thus, immunofluorescence experiments were carried out to visualize the distribution of DLAT in liver cancer cells." (PMID 40136640, 2025). "As expected, the soluble DLAT protein level decreased and the insoluble DLAT increased under elevated elesclomol-Cu incubation, and co-incubated sorafenib or erastin dramatically enhanced elesclomol-Cu augmented insoluble DLAT in liver cancer cells." (PMID 37277863, 2023). "Thus, immunofluorescence (IF) experiments were carried out to visualize the distribution of DLAT in liver cancer cells." (PMID 37277863, 2023). "Moreover, we used the Kaplan–Meier plotter tool to analyze the overall survival of patients with liver cancer based on the expression of the FDX1, DBT, GCSH, SLC31A1, and DLAT genes." (PMID 37763758, 2023).
hepatocellular carcinoma (7 papers, 2023 to 2026). A malignant tumor that arises from hepatocytes. "The findings demonstrated that MELK stimulated the expression of DLAT in hepatocellular carcinoma (HCC) cells through the activation of the PI3K/mTOR signaling pathway." (PMID 37949877, 2023). "To validate our previous results, we analyzed DLAT expression in hepatocellular carcinoma (HCC) using the GEO database and found that DLAT is highly expressed in HCC." (PMID 40302799, 2025). "Another research found that DLAT expression have positive relationship with PD-L1 in a clinical hepatocellular carcinoma (HCC) cohort, and DLAT was upregulated and correlated with poor prognosis." (PMID 38316885, 2024).
lung adenocarcinoma (7 papers, 2022 to 2024). A carcinoma that arises from the lung and is characterized by the presence of malignant glandular epithelial cells. "We found that older patients had increased DLAT expression o in GBMLGG and STAD, while had lower expression in lung adenocarcinoma (LUAD), ovarian serous cystadenocarcinoma (OV), READ, and testicular germ cell tumors (TGCT) than younger patients." (PMID 39574473, 2024). "By systematically analyzing the genetic alterations of 10 cuproptosis-related genes in lung adenocarcinoma, we found that CDKN2A, DLAT, LIAS, PDHA1, FDX1, GLS, and MTF1 were differentially expressed between lung cancer tissues and adjacent tissues." (PMID 36712848, 2022). "DLAT is upregulated in the LIHC, lung adenocarcinoma (LUAD), lung squamous cell carcinoma (LUSC), and stomach adenocarcinoma (STAD) tumors but is down-regulated in the head and neck squamous cell carcinoma (HNSC) and kidney renal clear cell carcinoma (KIRC) tumors in comparison with normal tissues." (PMID 36949759, 2023). "In this research, samples of lung adenocarcinoma were interrogated with cuproptosis-related genes, among which high expression of DLD, DLAT, PHDA1, PHDB, and CDKN2A were correlated with poor OS, while high expression of MTF1 was correlated with longer OS compared with the MTF1 low expression." (PMID 36003780, 2022).
lung cancer (7 papers, 2019 to 2025). A malignant neoplasm involving the lung. "In the cancer cell lines in the CCLE database, DLAT expression was relatively high in adrenal cancer, malignant rhabdoid tumor, and lung cancer and relatively low in kidney cancer, liposarcoma, and head and neck cancer." (PMID 37938155, 2023). "FDX1 affects the prognosis of lung cancer by altering the expression of cuproptosis-related signature (GLS, PDHA1, PDHB, MTF1, and DLAT), which more strongly confirms that the prognosis of lung cancer patients is closely related to the occurrence of cuproptosis." (PMID 36620594, 2022). "In a word, our study showed that FDX1, a key enzyme for cuproptosis, affected the prognosis of lung cancer patients by influencing the expression of GLS, PDHA1, PDHB, DLAT, and MTF1." (PMID 36620594, 2022).